TRAP1 (TNF receptor associated protein 1)
Diseases named in the same sentence as TRAP1 in open-access papers (continued):
Sharing a sentence is not in itself a finding about the gene and the disease.
breast carcinoma (continued). "Having found that Hsp90α and Trap1 play a role in one particular mouse mammary cancer model, we wondered to what extent one could extrapolate to human breast cancer." (PMID 28407697, 2017). "For breast cancer, increased expression of Trap1 has been reported." (PMID 28407697, 2017). "TRAP1 knockdown downregulates mitochondrial aerobic respiratory, sensitizes cells to lethal stimuli, and inhibits tumorigenesis; TRAP1 overexpression, however, enhances the capacity to cope with stress conditions, and is required for the tumorigenesis of breast cancer." (PMID 26517089, 2015). "In this study, we demonstrated that TRAP1 is overexpressed in breast cancer." (PMID 26517089, 2015). "We next examined whether TRAP1 modulates mitochondrial aerobic respiration of breast cancer cells under stress conditions." (PMID 26517089, 2015). "Interestingly, the expression of TRAP1 in human breast cancer specimens inversely correlates with tumor grade." (PMID 26517089, 2015). "We first analyzed TRAP1 expression in human breast cancer samples." (PMID 26517089, 2015). "Surprisingly, TRAP1 levels inversely correlate with breast cancer tumor grade (P = 0.042)." (PMID 26517089, 2015). "Since TRAP1 overexpression inhibits metastasis of breast cancer cells, we then examined whether TRAP1 impacts cell motility by regulating mitochondrial dynamics." (PMID 26517089, 2015). "As shown with small interfering RNA gene-silencing of TRAP1 in a lung cancer cell line and re-expression in a breast cancer cell line, TRAP1 expression seems not to be associated with apoptosis." (PMID 22978347, 2012). "Other HSP90 isoforms, such as HSP90B1 and TRAP1, may affect treatment responses in specific subtypes of breast cancer and this effect could be largely diluted in the analysis of a heterologous population." (PMID 22510516, 2012). "This suggests that TRAP1 may be a potential target for breast cancer therapy." (PMID 38098505, 2023). "Thus, TRAP1 expression was found to be increased in hepatocellular carcinoma, breast cancer, glioma, small cell lung cancer, and kidney, prostrate, ovarian, colorectal, and esophageal cancer, and it is correlated with advanced-stage metastatic tumors with poor prognosis." (PMID 35883436, 2022). "Furthermore, TRAP1 function is important in favouring resistance to paclitaxel, which is a microtubule stabilising/endoplasmic reticulum stress inducer agent that is widely used in breast cancer therapy, and to genotoxic agents, such as anthracyclines." (PMID 31052256, 2019). "Similarly, it has recently been published that invasive breast cancer cell lines have lower levels of Trap1; the same investigators found that when Trap1 is overexpressed in the invasive cell line MDA-MB-231 and cells are injected into the tail vein of immunodeficient mice, metastasis is inhibited." (PMID 28407697, 2017). "Moreover, the anti-oxidant activity of TRAP1 could contribute to cancer cell resistance to chemotherapeutics that elicit oxidative stress, especially in colorectal and breast cancer models." (PMID 28405578, 2017). "However, the role of TRAP1 in breast cancer tumorigenesis and metastasis remains elusive." (PMID 26517089, 2015). "TRAP1 knockdown downregulates mitochondrial aerobic respiratory, sensitizes cells to lethal stimuli, and inhibited tumor growth in MDA-MB-231 and MCF-7 breast cancer cells in vivo." (PMID 26517089, 2015). "Neither Hsp90a nor Trap1 are absolutely required for mammary tumor initiation, growth and metastasis induced by the polyoma middle T-antigen as oncogene." (PMID 28407697, 2017). "On the contrary, non-metastatic MCF-7 breast cancer cells express high level of TRAP1, and their mitochondria were tubular network-shaped." (PMID 26517089, 2015). "Only 1 of 481 (2%) breast cancer samples had two allele deletions on the TRAP1 coding region, and no patients carried a homozygous deletion of other HSP90 isoforms and HSF1, suggesting that loss of expression of HSP90 is a rare event in breast cancer." (PMID 22510516, 2012).
glioblastoma (14 papers, 2017 to 2025). The most malignant astrocytic tumor (WHO grade IV). "Another important protein of the Hsp90 family is TRAP1, a mitochondrial protein found to be associated with chemotherapeutic drug resistance, and significantly elevated in glioblastoma cell lines when compared to normal brain tissue." (PMID 36358853, 2022). "In this study, the loss of TRAP1 ameliorated the tumor-forming ability of glioblastomas in vivo." (PMID 35883436, 2022). "It was demonstrated that increased TRAP1 expression is required for proliferation, migration, and neurosphere formation in glioblastoma cells, and also for their resistance to temozolomide chemotherapy, which was associated with TRAP1-mediated metabolic reprogramming." (PMID 32268506, 2020). "Gamitrinib has been reported in glioblastoma that through suppressing TRAP1, gamitrinib can sensitize the GBM cells to temozolomide treatment." (PMID 38098505, 2023). "TRAP1 is highly expressed in tumors such as glioblastoma, colon, breast, prostate and lung cancers, but is low or even undetectable in normal cells." (PMID 38098505, 2023). "We performed an unbiased nanoLC-MS/MS mass spectrometry analysis to search for TRAP1 interactors in co-immunoprecipitation experiments on human U87 glioblastoma cells, where TRAP1 displays a pro-neoplastic activity." (PMID 35614131, 2022). "Knock-out of TRAP1 in glioblastoma cells sensitized them to temozolomide, decreased migration, induced cell apoptosis, and reduced cell proliferation." (PMID 36358853, 2022). "Here, we show that pan and selective HDAC inhibition is indeed synthetically lethal with TRAP1 inhibition in various model systems of glioblastoma, including patient-derived xenograft (PDX) cells." (PMID 32664214, 2020). "In this vein, following interrogation of public databases, we found that TRAP1 levels are significantly increased in glioblastoma tissue vs. normal brain tissue and in colonic adenocarcinoma vs. normal colonic tissue, respectively." (PMID 31181660, 2019). "One of the first studies on TRAP1 as a tumor biomarker was completed in glioblastoma, one of the most aggressive invasive brain tumors, highly resistant to therapy and heterogeneous at both the molecular and histological levels." (PMID 29621137, 2018). "TRAP1 levels are elevated in several malignancies, including glioblastoma, colon, breast, prostate and lung tumors and has been correlated with drug resistance." (PMID 29621137, 2018). "In this study, we briefly summarize the best-characterized contributions of TRAP1 in glioblastoma, prostate, colorectal, breast and non-small cell lung cancers." (PMID 29621137, 2018). "Moreover, it has been proposed that SIRT3 activates the mitochondrial chaperone TRAP1, thus contributing to the maintenance of cancer stem cells in a glioblastoma model." (PMID 35393510, 2022). "However, it was also proposed that TRAP1 is activated by SIRT3-dependent deacetylation in a glioblastoma model, making it difficult to draw a comprehensive picture." (PMID 35393510, 2022). "Here, we showed that the combined inhibition of TRAP1 by gamitrinib and histone deacetylases (HDAC1/HDAC2) through romidepsin or panobinostat caused synergistic growth reduction of established and patient-derived xenograft (PDX) glioblastoma cells." (PMID 32664214, 2020). "However, the activities of TRAP1 in glioblastomas seem to be conducive to cancer stemness development." (PMID 32268506, 2020). "Again, contradictory reports show that the absence of TRAP1 favors in vitro cell invasiveness through an increase in ROS levels and that cell motility and invasion of prostate cancer and glioblastoma cells are promoted by TRAP1 in conditions of limited nutrient availability." (PMID 28405578, 2017).
glioblastoma (continued). "Therefore, it is crucial to analyze the function of key proteins like the mitochondrial chaperone TRAP1, whose activity is directly related to the regulation of mitochondrial metabolism and ROS generation, positioning it as a central regulator in glioblastoma adaptation and survival." (PMID 40867215, 2025). "Therefore, TRAP1 is a promising target for drug design in glioblastoma therapy." (PMID 38098505, 2023). "TRAP1 might take a role in maintaining the stemness of glioblastoma stem cells." (PMID 38098505, 2023). "Taken together, we have provided evidence that simultaneous targeting of TRAP1 and HDAC1/2 is efficacious to reduce tumor growth in model systems of glioblastoma." (PMID 32664214, 2020). "Informed by a transcriptomic and subsequent gene set enrichment analysis, we demonstrate that inhibition of TRAP1 results in suppression of the cholesterol synthesis pathway in stem-like and established glioblastoma (GBM) cells by destabilizing the transcription factor SREBP2." (PMID 31181660, 2019). "Thus, it was demonstrated by Park and colleagues that interplay between TRAP1 mitochondrial chaperone and SIRT3 (mitochondria deacetylase sirtuin-3) increased adaptation to stress and maintained the stemness of the glioblastoma cells." (PMID 39015084, 2024). "Besides, TRAP1 is upregulated in Glioblastoma multiforme (GBM) compared with normal brain cells." (PMID 38098505, 2023). "We also observed a fast induction of TRAP1 following exposure to hypoxic conditions in several human tumor cell types, encompassing MIA PaCa-2 pancreatic cancer cells, U87 and U251 glioblastoma cells, BxPC3 pancreatic carcinoma cells, and ipNF95.6 plexiform neurofibroma cells." (PMID 33934112, 2021). "A transcriptome with subsequent gene set enrichment analysis demonstrated that stem-like glioblastoma (GBM) cells, NCH644, that were treated with a low concentration of TRAP1—inhibitor gamitrinib—displayed down regulated gene sets related to cholesterol and mevalonate biosynthesis." (PMID 31181660, 2019). "Informed by a drug screen approach to define synthetic lethal interaction for the novel TRAP1 inhibitor, gamitrinib, we validated whether or not global or selective HDAC inhibitors induce synergistic reduction of cellular viability in relevant model systems of human glioblastoma." (PMID 32664214, 2020).
Parkinson disease (11 papers, 2012 to 2025). A progressive degenerative disorder of the central nervous system characterized by loss of dopamine producing neurons in the substantia nigra and the presence of Lewy bodies in the substantia nigra and locus coeruleus. "Loss-of-function variants in TRAP1, including nonsense variants, were described in one late-onset Parkinson’s disease patient (homozygous p.R47*, and in three patients with functional disorders (heterozygous p.E216*, p.Y229*, p.R703*." (PMID 39333440, 2024). "Although the role of TRAP1 in the context of neurodegenerative diseases remains relatively unexplored, TRAP1 has been associated with Parkinson’s disease (PD) as an effector for PD-associated protein, PINK1." (PMID 35163711, 2022). "It is still under debate if TRAP1 is a causative gene of Parkinson’s disease, and therefore further research is required." (PMID 34829705, 2021). "This involvement of TRAP1 in mitochondrial redox control has been linked to the pathogenesis of several disorders, among which there are the Parkinson’s disease (PD) and ischemic damage." (PMID 28405578, 2017). "Trap1, on the other hand, mitigates neurotoxicity induced by the human α-Synuclein protein and addresses mitochondrial dysfunction, thereby rescuing neurodegeneration associated with Parkinson's disease (PD)." (PMID 39965405, 2025). "TRAP-1 is also crucial in some other pathologies such as Parkinson disease, as a mutation in PTEN-induced Putative Kinase (PINK1), which phosphorylates and activates TRAP-1, is present in the disease, where PINK1-mutated cells cannot activate TRAP-1 and apoptosis occurs." (PMID 37345199, 2023). "Likewise, loss of TRAP1 function in a patient with Parkinson’s disease was unimpactful." (PMID 35883436, 2022). "Finally, loss-of-function TRAP1 mutations have been identified in the brain of a patient with Parkinson’s disease, Leigh syndrome, and chronic functional symptomatology including pain, fatigue, and gastrointestinal dysmotility, and in congenital abnormalities associated with the kidney (CAKUT)." (PMID 35883436, 2022). "Likewise, TRAP1 appears to be protective in genetic models of neurodegeneration such as Parkinson’s disease where protein quality control in mitochondria plays a critical role." (PMID 35883436, 2022). "Impaired phosphorylation of TRAP1, due to mutated PINK1, leads to Parkinson’s disease." (PMID 30158430, 2018). "TRAP1 may contribute to the pathogenesis of neurodegenerative diseases, in particular, Parkinson’s disease." (PMID 23284813, 2012). "Recent studies have also identified TRAP1 as a direct target of PTEN-induced kinase 1 (PINK1), suggesting a potential link to Parkinson’s disease (PD) pathogenesis." (PMID 40098710, 2025). "Recently, TRAP1 was reported as a downstream phosphorylation target of PTEN-induced kinase 1 (PINK1), a gene involved in the onset of Parkinson’s disease, in rat and human cell lines." (PMID 23284813, 2012).
prostate carcinoma (11 papers, 2014 to 2023). A carcinoma that arises from epithelial cells of the prostate gland. "The inhibition of TRAP1 induction increases the apoptosis process in prostate cancer cells, which suggests that TRAP1 inhibitors (gamitrinibs (GA), mitochondrial matrix inhibitors) can be used in therapy for patients with advanced prostate glands." (PMID 35055079, 2022). "In apparent contradiction to what we observed with our genetic model, pharmacological inhibition of Trap1 and TRAP1 deletion in a prostate cancer model resulted in inhibition of tumor growth and reduced tumor incidence, respectively." (PMID 28407697, 2017). "TRAP1 silencing in androgen-independent prostate cancer cells enhanced apoptosis and treatment with mitochondria-directed HSP90 inhibitors (Gamitrinibs) selectively caused the death of prostate cancer cells." (PMID 29621137, 2018). "However, prostate cancer was not the only cancer type investigated for the role of TRAP1 in cancer progression." (PMID 29621137, 2018).
colon carcinoma (10 papers, 2011 to 2023). "Gamitrinib-TPP, inhibiting TRAP1 signaling pathways in colon cancer, can disrupt redox homeostasis and induce cell death." (PMID 38098505, 2023). "Increased ROS production upon TRAP1 silencing was also previously reported in colon cancer cells (HCT116), lung cancer cells and HeLa cells upon exposure to H2O2." (PMID 36829938, 2023). "Accordingly, 5-fluorouracil-, oxaliplatin-, and irinotecan- resistant clones of HT-29 colon cancer cells show increased expression of TRAP1 compared to their sensitive counterpart." (PMID 31947673, 2020). "This in vitro observation was supported by reduced activity of the complex II in colon cancer samples with high expression of TRAP1 as compared to those with low TRAP1." (PMID 31947673, 2020). "In support of these data, TRAP1 expression was inversely correlated to SDH activity in colon cancer specimens, in which TRAP1 expression was higher in comparison with the relative healthy surrounding mucosas." (PMID 29621137, 2018). "Tsai report that treatment with both an NRF2 inhibitor and a TRAP1 inhibitor may potentially overcome colon cancer resistance by raising cellular ROS level." (PMID 38098505, 2023). "Several new derivatives were evidenced to accumulate in the mitochondrial fraction of colon carcinoma cells, and one compound in particular was proven to be good at inhibiting recombinant TRAP1 ATPase activity and at reducing cell growth and inducing apoptotic cell death in colon carcinoma cells." (PMID 31947673, 2020). "Noteworthy, a small subgroup of colon cancers is characterized by TRAP1 levels below normal mucosa." (PMID 28177905, 2017). "Finally, TRAP1 positive expression and its prognostic value are more evident in left colon cancers." (PMID 28177905, 2017). "Finally, TRAP1 capacity to predict poor prognosis were shown to be conserved in left CRCs, thus supporting the hypothesis that the upregulation of TRAP1 protein network may represent a further biological difference between right and left colon cancers." (PMID 28177905, 2017). "Thus, it is intriguing to speculate that TRAP1 upregulation may represent an early mechanism used by colon cancer cells to adapt to unfavorable environmental conditions and, thus, activate a number of pathways responsible for malignant transformation and tumor progression." (PMID 28177905, 2017). "In addition, TRAP1-silenced colon carcinoma cells exhibited lack of clonogenic ability in vitro and tumor formation in mice xenografts, thus supporting the relevance of TRAP1 in early phases of colon carcinogenesis." (PMID 28177905, 2017). "By contrast, the statistical significance in overall survival between TRAP1-positive and negative tumors is lost in right colon cancers (HR 2.65; 95% C.I. 0.8-8.6; p=0.1), even though the lack of significance is likely due to the low number of right colon cancers in our series." (PMID 28177905, 2017).
lung carcinoma (10 papers, 2012 to 2025). "This regulatory mechanism has been demonstrated in breast, colorectal, and lung carcinoma cell lines and tumor samples, highlighting TRAP1 as a promising therapeutic target in these malignancies." (PMID 41226319, 2025). "It has been posited that TRAP1 has pro-oncogenic functions based on its increased presence in several types of cancer, such as colorectal, breast, prostate, nasopharyngeal, and lung carcinomas." (PMID 37508418, 2023). "Patients with lung disease have a higher level of cytoplasmic HSP90 homologs (HSP90AA1 and HSP90AB1) in relationship to mitochondrial HSP90 homolog (TRAP1), whereas patients with lung cancer have a higher level of TRAP1 to the level of cytoplasmic HSP90." (PMID 34692733, 2021). "In lung cancer, TRAP1 silencing sensitizes cells to mitochondrial mediated cell death driven by VP-16 and β-hydroxyisovalerylshikonin." (PMID 31947673, 2020). "This suggests that, at least in these tumors, the TRAP1-dependent regulation of cell proliferation relies on metabolic control, in keeping with previous observations in breast and lung cancer cell lines." (PMID 29621137, 2018). "However, others have demonstrated that TRAP1 knockdown inhibits cell survival in different lung cancer cells, H1299 (human non-small cell lung carcinoma cell) and A549 (adenocarcinomic human alveolar basal epithelial cells)." (PMID 36829938, 2023). "Additionally, TRAP1 (TNF receptor associated protein 1) has been indicated to regulated the apoptosis in lung cancer and thyroid carcinoma cells, while TRAP1’s role in the prognosis of OS is firstly revealed in our study as far as we know." (PMID 35504036, 2022). "Higher levels of both constitutive and stress-inducible HSP90 isoforms in relationship to mitochondrial HSP90 isoform TRAP1 are associated with benign lung diseases such as PM and COPD, whereas a higher level of TRAP1 to HSP90AA1 and HSP90AB1 is associated with lung cancer." (PMID 34692733, 2021). "Downregulation of TRAP1 leads to the degradation of proliferation markers, such as Ki67, CDK1, and MAD2, in breast, colorectal, and lung cancer models, sensitizing these cells to agents that target the cell cycle machinery." (PMID 41226319, 2025).